LOX (lysyl oxidase)
Diseases named in the same sentence as LOX in open-access papers (continued):
Sharing a sentence is not in itself a finding about the gene and the disease.
tumor (continued). "In most tumor tissues, ECM remodeling is characterized by alterations in the production and deposition of collagen, all accompanied by changes in the expression of remodeling enzymes such as matrix metalloproteinases (MMP), lysyl oxidase (LOX), and lysyl oxidase-like (LOXL) proteins, among others." (PMID 40906383, 2025). "Additionally, our findings revealed that patients with triple‐negative breast cancer receiving neoadjuvant chemotherapy showed lower levels of LOX and LOXL2 expression in their tumour tissues than those who were sensitive to taxanes, anthracyclines and platinum agents." (PMID 40179101, 2025). "In the majority of tumour tissues, ECM remodelling is marked by heightened collagen synthesis and deposition, often coincident with the up‐regulation of various remodelling enzymes, including MMPs, lysyl oxidases (LOX and LOXLs) and proteins from the WNT1‐inducible signalling pathway." (PMID 39270064, 2024). "Since these hypoxic conditions are not ameliorated due to the lack of new blood vessels, LOX is likely continuously secreted into the tumor as hypoxia increases, which could explain the doubling in ECM stiffness we reported after nintedanib treatment." (PMID 37190331, 2023). "Matrix stiffness can seriously affect the metastatic process, and the following hypothesis has been proposed: FN allows a softer ECM that facilitates tumor vascularization for tumor growth until hypoxia slowly erases FN and stiffens the ECM upon the crosslinking of collagen induced by LOX." (PMID 36497411, 2022). "Both local and global measurements confirm the normalization of tumor tissue mechanical properties mediated by LOX inhibition with a drastic reduction in the linearized tightly packed collagen fibers that contribute to tumor stiffness heterogeneity and global enhancement in non-treated KPC tumors." (PMID 34106045, 2021). "Hypoxic exosomes was found to be enriched with proteins such as protein-lysine 6-oxidase (LOX), thrombospondin-1 (TSP1), and VEGF, and a disintegrin and metalloproteinase with thrombospondin motifs 1 (ADAMTS1), which are well-studied contributors to tumor progression, metastasis, and angiogenesis." (PMID 34444030, 2021). "While, in our study, by administration of the LOX recombinant protein (rhLOX) before and after the tail vein injection of PC3 tumor cells (a CRPC cell line), we showed that rhLOX treatment may reduce the tumor metastasis probability, and consistent with the in vitro cell migration data we presented." (PMID 35003355, 2021). "However, the relationship between tumor metastasis, collagen I, LOX, and integrin activation in the context of EMT has not been fully elucidated at the cellular and molecular levels." (PMID 33391538, 2021). "Alternatively, increases in BMP1 may have tumour suppressive effects in Ras transformed cancers, where post-translational processing in cells highly expressing LOX and LOXL1 would increase levels of the tumour suppressive LOX pro-peptide." (PMID 33513979, 2021). "D-Pen has the ability to remove Cu in vivo and the combination of D-pen and Cu could lead to cell death in endothelial cells and lymphocytes possibly as a result of ROS production and LOX and ICAM inhibition, eventually suppressing tumour growth and vascularization." (PMID 34604310, 2021). "Expression of genes such as AEBP1, SNAI1, and LOX similarly increased after the first week of tumor progression, although these changes could not be quantitatively compared to week 1 due to undetermined Cq values at this time point." (PMID 34868914, 2021). "Accordingly, in this study, we hypothesized that in a tumor microenvironment, RT-R-MDA-MB-231 cells, which contain more CSCs than MDA-MB-231 cells, induce HIF-1α expression and LOX secretion, and then finally premetastatic niche formation, more than MDA-MB-231 cells do." (PMID 33126606, 2020).
tumor (continued). "The activated EGFR is known to regulate LOX expression via the PI3K/AKT, MEK/ERK and SAPK/JNK pathways, as observed in human non-small cell lung carcinoma cell lines and confirmed in vivo in an orthotopic metastasis mouse model and in human tumor tissue microarray analysis." (PMID 32708046, 2020). "Notably, LOX could be a potential therapeutic target for invasive BC, since selective LOX inhibition reduces angiogenesis, BCAF activation, and tumor growth." (PMID 32604738, 2020). "Transforming growth factor-β1 (TGF-β1), lysyl oxidase (LOX), cystatin (CST3), plasminogen activator inhibitor-1 (PAI-1), matrix metalloproteinases (MMPs) and tissue inhibitors of metalloproteinases (TIMPs) proved to be involved in the turnover of ECM, wound healing, tumor invasion and metastasis." (PMID 33143101, 2020). "Although there is an interplay between LOX and cell-surface integrin receptors in the tumor microenvironment, and between LOX and integrin-mediated mechano-transduction, no direct interaction of a member of the LOX family with an integrin has been described so far." (PMID 33383846, 2020). "However, evidence has indicated that the tumour suppressor activity of LOX is dependent on the pro-peptide domain and not the enzyme catalytic domain." (PMID 32912229, 2020). "Inhibition of LOX activity decreased levels of fibrillar collagen, increased tumor infiltration of macrophages and neutrophils, eliminated metastases in models of orthotopic breast and transgenic pancreatic cancer, and enhanced drug delivery in a PDAC tumor model." (PMID 30105016, 2018). "LOXL2 is a member of the lysyl oxidase gene family which catalyzes the crosslinking of extracellular collagen and elastin resulting in increased ECM stiffness and subsequent activation of the kinases FAK and SRC, which enable tumor cells to proliferate and invade." (PMID 30473751, 2018). "In addition to this, our previous work has shown that overexpression of LOX in the non-metastatic SW480 cell line leads to increased tumour cell proliferation and metastasis both in vitro and in vivo." (PMID 28947950, 2017). "However, significantly increased expression of LOX in the nucleus was observed in lymph node metastases when compared with primary tumour in both non-RT and RT groups (P = 0.002 and P = 0.0007, respectively)." (PMID 28947950, 2017). "When examining cytoplasmic immunostaining patterns of LOX, we observed higher levels of LOX expression in primary tumour tissue (79% of 77 (non-RT), and 83% of 60 (RT)) compared to normal mucosa (32% of 62 (non-RT), and 63% of 54 (RT)) for both non-RT (P < 0.001) and RT (P = 0.014) patients." (PMID 28947950, 2017). "Moreover, LOX expression was significantly higher in tumor tissue of metastatic ccRCCs than in non-metastatic ccRCCs." (PMID 27336447, 2016). "Moreover, LOX mRNA expression was higher in AT-1 tumours at day 3 compared to at day 6 and 10 while LOX mRNA expression in the tumour-adjacent non-malignant prostate tissue was increased at day 10 compared to the earlier time points." (PMID 26804196, 2016). "Increased LOX expression in the tumour-adjacent non-malignant tissue at day 10 could thus be part of an ECM remodelling response in the tumour-bearing organ." (PMID 26804196, 2016). "One reason for the high LOX levels in prostate TINT could be that the tumor, by mechanisms unknown, induces LOX expression in non-malignant prostate cells." (PMID 26501565, 2015). "Here, we saw no tumor acceleration at any stage by LOX inhibition." (PMID 26077591, 2015). "Interestingly, conditioned media derived from irradiated, LOX siRNA-transfected cells did not stimulate the invasive capacity of naïve A549 tumor cells, thereby demonstrating LOX-specificity." (PMID 25052686, 2014). "However, neither LOX itself (which enables neoplasia by cross-linking collagen chains) nor the three human LOX homologs exhibited any genomic alterations." (PMID 25236784, 2014).
tumor (continued). "The effects of LOX on growth, invasiveness and migration appear to be more important in metastatic growth than in primary tumour formation, exemplified by pronounced effects of LOX inhibition on metastasis formation, but not on primary tumour growth in an orthotopic xenotransplantation model." (PMID 25141126, 2014). "In the present study, the mean and median LOX expression levels were lower in ER negative vs. positive tumours, however, there was a clearly separated subgroup of ∼14% ER negative patients with considerably higher LOX expression levels than all other ER negatives." (PMID 25141126, 2014). "We investigated whether hypoxia could promote tumor invasion and migration via HIF-1α and LOX." (PMID 23545606, 2013). "In addition, when considering inhibitors of CAIX, LOX, or CXCR4, selection of patients should be based on examination of expression levels of these target genes in tumor biopsies or by PET imaging based on tumour retention of radiolabeled antibodies (for example, against CAIX)." (PMID 22128892, 2011). "LOX mRNA expression displayed a species difference with a strong positive correlation between fold-induction and hypoxic extent in the human tumor model and no or a weak inverse relationship in the murine tumor model." (PMID 21306648, 2011). "Although LOX showed no significant expression differences across T stages, it may indirectly affect tumor growth and invasiveness by altering the extracellular matrix surrounding the tumor." (PMID 40464853, 2025). "Notably, selective upregulation of protein-lysine 6-oxidase (LOX-6), VEGF, thrombospondin-1 (TSP1) and other proteins has been observed, which converge in the tumor neovascularization region and may serve as key players in tumor angiogenesis." (PMID 37779868, 2023). "Furthermore, the silencing of miR-92a could significantly suppress tumor invasion and growth, while the enhancement of miR-29a expression levels could also put a break on metastatic dissemination via targeting VEGFA, LOXL2, and LOX." (PMID 37108330, 2023). "Moreover, as these tissue arrays do not provide information about neoadjuvant pharmacotherapy, chemotherapy, or radiotherapy, we could not perform any detailed analyses in regard to LOX levels and tumor stage." (PMID 34815382, 2021). "Indeed, in the in vivo xenograft model, CD24−/low/CD44+ cell-injected mice exhibited greatly increased tumor growth and lung metastasis, accompanied by upregulated expression of EMT-related proteins and increased HIF-1α and ESM-1 levels in tumors and circulating LOX levels in plasma." (PMID 34502547, 2021). "Finally, LOX inhibition also significantly decreased the surface covered by thick and densely packed collagen fibers in EGI-1, KPC, and MMTV-PyMT model, correlating with the significant decrease in average tumor stiffness and in the proportion of stiff areas measured in vivo." (PMID 34106045, 2021). "Taken together, these data indicate that, irrespective of whether LOX is secreted from the tumor cell, surrounding fibroblasts in the connective tissue, or the endothelial cells of nearby vessels, LOX enhances tumor progression in the tumor cell microenvironment." (PMID 28036074, 2016). "However, although the mean and median LOX expression levels in ER negative tumours were lower than in ER positive tumours, there was a distinct subgroup of ∼14% (8/58) ER negative patients whose LOX expression levels were considerably higher than in all other ER negative tumours." (PMID 25141126, 2014). "LOX cross-linking collagen IV in the basement membrane was essential for recruitment of CD11b+ myeloid cells, which could secrete MMP-2 to resolve collagen to enhance the tumor invasion and recruitment of BMDCs and metastasizing tumor cells to pre-metastatic niche." (PMID 24587996, 2014).
tumor (continued). "In addition, we found that the lysyl oxidase inhibitor β-aminoproprionitrile (βAPN) largely reduced fibrillar collagen (unpublished data) and enhanced the CHT–TF transmigration of neutrophils, leading to a significant increase of tumour cell invasion and subsequent formation of micrometastases." (PMID 22374800, 2012). "The only model that does not respond to LOX inhibition by stiffness reduction is MET-1, in line with our previous data showing an absence of tumor stiffening during tumor growth." (PMID 34106045, 2021). "Although various malignant tumors express high levels of lysyl oxidase (LOX) and though its role in tumor progression is well-defined, there is a lack of sensing techniques to target LOX." (PMID 34572752, 2021). "Differences in gene expression across all cases when comparing tumor and non-tumor samples were not statistically significant with the exception of CA9 and LOX (p<0.05)." (PMID 26317980, 2015). "Similar to the survival benefits induced by LOX inhibition, we found that CLOCK inhibition using SR9009 combined with anti-PD1 therapy resulted in survival extension, but did not cure any tumor-bearing mice, in CT2A and 005 GSC models." (PMID 39352749, 2024). "Unlike LOX, LOXL2 crosslinks and stabilizes insoluble collagen deposition in tumor tissues." (PMID 39329988, 2024). "LOX, as an extracellular matrix (ECM) remodeling enzyme, might stiffen the ECM and support angiogenesis surrounding the tumor tissue, thereby contributing to the TACE nonresponse phenotype." (PMID 35111225, 2022). "The requirement of LOX-dependent ECM crosslinking and stiffness for Endo180-dependent tumor cell migration is aligned with the finding that non-enzymatic crosslinking of basement membrane matrix coupled with Endo180-dependent mechanotransduction triggers epithelial cell invasiveness." (PMID 26567111, 2016). "Additionally, endothelial cells were predominantly stained for LOX in GBM cases, with significant differences of this tumor group and non-neoplastic and AGI, AGII and AGIII groups." (PMID 25790191, 2015). "Therefore, tumor uptake and blocking effects in vivo in the presence of BAPN indicate both a specific interaction with LOX and non-specific processes." (PMID 26265048, 2015). "While treatment with PXS-5505 or FOX alone had no impact on tumor growth relative to the vehicle, the combination of PXS-5505 with FOX significantly delayed tumor growth compared to all other cohorts, strongly suggesting pan-LOX inhibition abrogates resistance to chemotherapy." (PMID 39101793, 2024). "Taken together this shows that the target for LOX was absent in the stroma of established tumours and reduced in the surrounding non-malignant tissue, which may explain why BAPN treatment did not inhibit tumour growth at later time points." (PMID 26804196, 2016).
cancer (400 papers, 2007 to 2026). A tumor composed of atypical neoplastic, often pleomorphic cells that invade other tissues. "For instance, the cancer-associated fibroblasts (CAFs) in oral tumors increase matrix stiffness by producing LOX, which in turn promotes cancer progression through the FAK phosphorylation pathway." (PMID 39895789, 2025). "Aberrant LOX activity has been associated with a multitude of health disorders, including cutaneous, pulmonary, fibrotic, cardiovascular diseases, and cancer." (PMID 40661776, 2025). "Lysyl-oxidase (LOX) plays a significant role in cancer-associated ECM stiffness by crosslinking ECM components." (PMID 40822927, 2025). "Since active LOX enzyme levels are strongly associated with poor clinical outcomes, our data provide at least one possible pathway for the observed poor cancer outcomes associated with rs1800449 polymorphism." (PMID 37298359, 2023). "We have provided initial findings that point to a link between the LOX polymorphic variant in the enzymatically inactive propeptide region and increased cancer susceptibility and worse outcomes." (PMID 37298359, 2023). "Another study demonstrated the strong association between lysyl oxidase (LOX) upregulation and the overall ratio of insoluble to soluble collagen in para-carcinoma tissues and renal biopsies." (PMID 37569677, 2023). "On one hand, the increased expression of GPX7 and LOX was associated with the chemotherapy resistance of cancer cells to Fluphenazine, arsenic trioxide, nellarabine, erlotinib, and lenvatinib." (PMID 35699863, 2022). "We also describe attempts that have been made, and are still on-going, that focus on the development of efficient lysyl oxidase inhibitors for the treatment of various forms of cancer, and of diseases associated with abnormal fibrosis." (PMID 35682926, 2022). "Increased LOX expression and enhanced stiffness in the tumor microenvironment are both associated with cancer progression and metastasis in solid tumors such as breast, colorectal, and prostate cancers." (PMID 36430490, 2022). "Increased LOX expression and activity has been linked to cancer development and metastasis formation in various tissues and high LOX protein levels correlate with poor clinical prognosis." (PMID 34295891, 2021). "miRNA-associated regulation of LOX expression is a critical mechanism in the progression and metastasis of cancer cells." (PMID 34815382, 2021). "LOXL2, a prototypical lysyl oxidase, is implicated in the promotion of cancer cell invasion, metastasis and angiogenesis, as well as in the malignant transformation of solid tumors." (PMID 34943209, 2021). "Studies have reported that the human population with LOX G473A variants exhibits a higher risk of cancer in lungs, stomach, colon-rectum, breast, and cervix." (PMID 35054220, 2021). "LOX is also highly expressed in Lkb1-deficient lung adenocarcinomas, where it is required for enhanced cancer cell proliferation and invasiveness." (PMID 31130685, 2019). "Stiffening of the ECM due to enhanced lysyl oxidase activity is also associated with cancer progression and fibrosis." (PMID 31614631, 2019). "Elevated LOX activity has been clinically associated with increased collagen cross-linking, fibrosis, and elevated risk of cancer metastasis." (PMID 30287763, 2018). "Further research addressing the contrasting roles of mature LOX/LOXL and LOX-pp in cancer progression, and a better understanding of LOX-associated signaling in tumorigenesis will be required for the success of such therapeutics." (PMID 29732010, 2018). "By possible relationship to ROS and EMT cancer cell movements, lysyl oxidase is an enzyme that promotes extracellular matrix collagen crosslinking and stiffness as a hypoxia-related protein which is associated with cancer metastasis." (PMID 29984367, 2018). "The study also focused on LOX, encoding a lysyl oxidase known to be involved in keratinocyte differentiation and to be directly regulated by miR-30a in cancer cells." (PMID 29165315, 2017).